SLC37A1 (solute carrier family 37 member 1)
Description:
Inorganic phosphate and glucose-6-phosphate antiporter. May transport cytoplasmic glucose-6-phosphate into the lumen of the endoplasmic reticulum and translocate inorganic phosphate into the opposite direction. Independent of a lumenal glucose-6-phosphatase. May not play a role in homeostatic regulation of blood glucose levels.
Synonyms: G3PP; SPX1
Tractability: Antibody: UniProt predicts a signal peptide or a membrane-spanning region. PROTAC: ubiquitination databases record sites on it.
Gene: Protein-coding gene on chromosome 21 (42,495,994 to 42,581,440, forward strand). Ensembl gene ENSG00000160190.
Subcellular location: Endoplasmic reticulum membrane
Pathways (Reactome):
Metabolism: Gluconeogenesis
Gene Ontology:
Molecular function: glucose 6-phosphate:phosphate antiporter activity; transmembrane transporter activity
Biological process: glucose-6-phosphate transport; phosphate ion transmembrane transport; transmembrane transport
Cellular component: endoplasmic reticulum membrane; membrane
Genetic constraint (gnomAD): Loss-of-function variants: 46 observed, 72.02 expected, observed/expected ratio (o/e) 0.64, 90% interval 0.5 to 0.82. The upper end of that interval is the gene's LOEUF score, 0.82, which puts it in group 3 of 6, group 1 being the genes least tolerant of losing a copy. Missense variants: 544 observed, 687.86 expected, observed/expected ratio (o/e) 0.79, 90% interval 0.74 to 0.85. Synonymous variants: 263 observed, 287.5 expected, observed/expected ratio (o/e) 0.91, 90% interval 0.83 to 1.01.
Homologues: Orthologues: chimpanzee SLC37A1 (99% identical), macaque SLC37A1 (93% identical), pig SLC37A1 (87% identical), mouse Slc37a1 (86% identical), guinea pig SLC37A1 (86% identical), dog SLC37A1 (85% identical), rat Slc37a1 (84% identical), rabbit SLC37A1 (69% identical), zebrafish slc37a1 (67% identical), tropical clawed frog slc37a1 (67% identical), Drosophila melanogaster MFS16 (44% identical), Drosophila melanogaster Picot (17% identical), and 43 more. Paralogues in human: SLC37A2 (56% identical), SLC37A3 (33% identical), SLC17A5 (18% identical), SLC17A4 (17% identical), SLC17A7 (17% identical), SLC17A2 (17% identical), SLC17A6 (17% identical), SLC17A8 (17% identical), SLC37A4 (17% identical), SLC17A1 (15% identical), SLC17A3 (15% identical), SLC17A9 (14% identical).
Diseases named in the same sentence as SLC37A1 in open-access papers:
SLC37A1 is named in the same sentence as 10 diseases in open-access papers, as found by Europe PMC text mining. Sharing a sentence is not in itself a finding about the gene and the disease. The quoted sentences say what the papers report.
brain cancer (1 paper, 2023). A primary or metastatic malignant neoplasm affecting the brain. "Total RNA was extracted and gene expression of G6PC1-3 as well as of SLC37A1-4 members analyzed by qPCR in four human brain cancer cell lines and from clinically annotated brain tumor cDNA arrays." (PMID 38034009, 2023).
breast carcinoma (1 paper, 2011). "SLC37A1 is reported to be up-regulated by epidermal growth factor in breast cancer cells, leading to the suggestion that its biological role might be involved in phospholipid biosynthesis." (PMID 21949678, 2011).
colon tumor (1 paper, 2024). "SLC37A1 expression significantly increases in colon tumor tissues, which is associated with hematogenous metastasis and glycolipid metabolism, indicating a potential role in colon cancer progression." (PMID 38534987, 2024).
congenital hyperinsulinism (1 paper, 2018). "SLC37A1 seems to be required for lipid biosynthesis in cancer cell lines, SLC37A2 has been proposed as a vitamin D and a phospho-progesterone receptor target gene, while mutations in the SLC37A3 gene appear to be associated with congenital hyperinsulinism of infancy." (PMID 29719821, 2018).
ovarian carcinoma (1 paper, 2023). A malignant neoplasm originating from the surface ovarian epithelium. "Dysregulation in the global G6Pase system has been implicated in various cancers, including ovarian cancer and HCC, but the specific contributions of the G6PC1-3 and SLC37A1-4 isoforms remains unclear." (PMID 38034009, 2023).
cancer (4 papers, 2018 to 2023). A tumor composed of atypical neoplastic, often pleomorphic cells that invade other tissues. "One of those genes (SLC37A1) is a Pi-linked glucose-6-phosphate antiporter and appears to be involved in breast and colorectal cancers." (PMID 34828336, 2021). "SLC37A1 gene appears to be involved in breast and colorectal cancers." (PMID 29719821, 2018). "The hypothetical role of SLC37A1 as a G3P exchanger has been postulated in cancer cells." (PMID 29719821, 2018). "Notably, in the same work the SLC37A1 protein localization in the ER was also demonstrated, supporting the hypothesis that this protein could import G3P into the ER lumen to sustain phospholipid biosynthesis, required to promote cancer progression." (PMID 29719821, 2018).
SLC37A1 also shares sentences with these, for which no sentence is quoted: brain tumor (1 paper); glioblastoma (1); kidney stone (1); low grade glioma (1).